SQSTM1 (sequestosome 1)
Diseases named in the same sentence as SQSTM1 in open-access papers (continued):
Sharing a sentence is not in itself a finding about the gene and the disease.
infection (continued). "The immunoblot data also show that HELLS/SMARCA6, RECQL4, SQSTM1/p62, and DCAF1 each exhibit decreased protein abundances during Ad5 WT infection, consistent with the WCP data." (PMID 34463575, 2021). "Consistently, the infection of Vero B4 cells with MERS-CoV leads to increased levels of the autophagic receptor/substrate, SQSTM1, and a higher LC3-II/LC3-I ratio, indicating autophagosome accumulation." (PMID 34440791, 2021). "The WCP data suggest that each of the selected proteins (HELLS/SMARCA6, RECQL4, SQSTM1, and DCAF1) are decreased during Ad5 WT infection, with distinct abundance change profiles." (PMID 34463575, 2021). "To verify the cellular status of autophagy and to monitor autophagic flux during HCoV-OC43 infection, we evaluated the expression of LC3 and p62/SQSTM1 proteins." (PMID 32674356, 2020). "The impairment of dsRNA-induced apoptosis late in infection was controlled by the viral 3C-protease (3Cpro), which disrupted RIPK1-TRIF/FADD /SQSTM1 immune-complexes." (PMID 29449668, 2018). "Yet, in HRV-A16 infection the RIPK1 complex was substantially altered due to 3Cpro, and consisted of the 60 kDa RIPK1 fragment, procaspase-8, 3ABC and/or active 3Cpro and p62/SQSTM1." (PMID 29449668, 2018). "By using different readouts, we showed that endogenous LC3, GFP-LC3 and SQSTM1 puncta, corresponding to autophagosomes, accumulate in HSV-1 infected cells during the early times of the infection." (PMID 27509841, 2016). "Additionally, this virus promotes the degradation of STING (Stimulator of Interferon Genes, a key molecule of the innate immune system) through DDIT3 and Sequestosome 1 (SQSTM1) upregulation, which suppresses type I IFN responses at early stages of infection." (PMID 40943382, 2025). "Interestingly, we found that LAP inhibition reduced the accumulation of SQSTM1/p62 and LC3-II during infection but increased the portion of LC3-I, suggesting that T. whipplei uptake by LAP contributes to the blockade of the autophagic flux." (PMID 40395986, 2025). "Considering the significance of the AMPK-mTOR pathway in regulating autophagy, we measured the effects of metformin on phosphorylated mTOR, a crucial autophagy pathway regulator, and SQSTM1, an autophagosome adapter and marker of autophagic flux, during SFTSV infection or rapamycin treatment." (PMID 40391966, 2025). "Interestingly, a study carried out in HEL cells revealed that HSV-1 reduces the levels of SQSTM1/p62 and OPTN1, dependent on proteasome activity during the early steps of infection." (PMID 39120287, 2024). "In combining this with previous results, we believe that DK/212 infection enhances the expression of TRIM21 and competitively binds to SQSTM1 to reduce the release of NRF2 from the KEAP1-NRF2 complex, which ultimately destroys the antioxidant system of cells and promotes ferroptosis." (PMID 38542289, 2024). "Furthermore, we evaluated the status of autophagy markers p62 (also known as sequestosome-1 [SQSTM1]) and autophagic vesicle formation marker LC3B during infection of WT BMDMΦ by Western blot analyses." (PMID 37819111, 2023). "While starvation reduced the levels of SQSTM-1 in WT infections to that of non-infected cells, no change was observed in Cig57 transposon mutants." (PMID 33251162, 2020). "LC3-I to LC3-II conversion was observed in both HOS and A549 cells with time post-SFV4 infection, and SQSTM1/p62 levels decreased in HOS cells at early phase of infection and decreased in A549 overtime during infection, indicating that the cargo in the autophagosome were degraded." (PMID 31969562, 2020). "Following infection with SRV-8, the autophagic proteins LC3 and p62/SQSTM1 interacted with procaspase-8, which might be responsible for the activation of the caspase-8/-3 cascade and apoptosis in SRV-8-infected Jurkat cells." (PMID 32244330, 2020). "Its activation could lead to autophagy (SQSTM1), apoptosis of the infected cells and the production of other cytokines (CARD17) in response to the infection." (PMID 31211814, 2019).
infection (continued). "The cleavage of SQSTM1/p62 was recently confirmed upon PV, EV-D68, and HRV1A infection." (PMID 30475087, 2019). "In CQ-treated cells, the level of SQSTM1 was notably increased regardless of infection, which confirmed the effect of lysosomal protease inhibition of CQ." (PMID 28059118, 2017). "To determine whether MV-Edm infection enhances autophagic flux, we analyzed both lipidation of MAP1LC3B in presence of chloroquine and expression of SQSTM1." (PMID 25004098, 2014). "Interestingly, we observed a distinct migration pattern for SQSTM1/p62, suggesting it may be post-translationally modified by HSV-1 during early stages of infection, starting from 4 hpi." (PMID 39120287, 2024). "Despite a certain degree of transcriptional activation at 48 h post-infection, the expression level of the long-lived autophagy protein SQSTM1 did not substantially vary over the course of DUGV infection and, in particular, did not progressively increase after infection." (PMID 36298785, 2022). "Furthermore, C. burnetii lacking Cig57 did not accumulate SQSTM-1 during infection as seen in WT strains." (PMID 33251162, 2020). "However, unlike Cig57, SQSTM-1 was still increased during infection with CvpF transposon mutants and reduced by starvation-induced autophagy." (PMID 33251162, 2020). "Thus, in line with the observations made above, our results suggest that R. australis fails to induce autophagy flux at the very early stage of infection, considering that the levels of p62/SQSTM1 did not reduce upon infection." (PMID 30297526, 2019). "Interestingly, we found that nuclear fragmentations typical for apoptosis following MV-Edm infection occurred exclussively in autophagy knockdown cells treated with ATG7, BECN1 and SQSTM1 siRNA, respectively, whereas nuclei within syncytia remained intact in control siRNA treated cells." (PMID 25004098, 2014). "Interestingly, p62/SQSTM1 was not significantly increased by infection itself." (PMID 38915921, 2024). "Furthermore, inhibition of autophagy by Baf-A1 challenge resulted in further accumulation of both MAP1LC3B-II and SQSTM1 in AGS cells after 6 h of Hp-WT or Hp-ΔcagA infection, suggesting that H. pylori CagA did not inhibit the fusion of autophagosomes with lysosomes." (PMID 28983474, 2017). "As for SQSTM1 and BECN1, there was no change in transcription at 24 h post-infection, but there was a noticeable increase at 48 h post-infection." (PMID 36298785, 2022). "The downregulation of SQSTM1/p62 and OPTN in HSV-1 infection seems to happen early on during infection without the requirement of viral replication, requiring calcium and ICP0 cytoplasmic localization." (PMID 34167456, 2021). "We finally investigated the p62/SQSTM1 levels, and found that they were strongly reduced late in HRV-A16 infection but not after poly I:C treatment." (PMID 29449668, 2018). "Several genes including MAP1LC3B, SQSTM1 and PLEKHM1 demonstrated a pattern wherein expression level was significantly downregulated upon SARS-CoV-2 infection (vs. no infection) in DMSO-treated ALOs and significantly upregulated in response to RMC-113 treatment." (PMID 38659941, 2024). "In support of this hypothesis, cells within the infected culture that controlled infection effectively (zero vRNA counts) achieved greater suppression of SQSTM1 and WDFY3 expression than cells that failed to control infection (1+ viral counts)." (PMID 38659941, 2024). "The abundance of GABARAPL1, SQSTM1, and LC3BII/I ratio increased upon Sp infection with CSE pre-exposure compared to the medium control, showing that Sp infection has no additional effects on the effects induced by CSE pre-exposure on mitophagy adaptor protein levels." (PMID 35681466, 2022). "Furthermore, re-expression of SAC1 WT, but not SAC1 C389S or BFP, reduced the levels of NDP52+, SQSTM1+, and LC3+Salmonella in SACM1L KO cells at 2 h post-infection, revealing that SAC1 phosphatase activity is necessary for functional xenophagy." (PMID 34320354, 2021).
neurodegenerative disease (40 papers, 2013 to 2026). A disorder of the central nervous system characterized by gradual and progressive loss of neural tissue and neurologic function. "SQSTM1, a scaffold protein with a critical role in macroautophagy, has been previously linked to several neurodegenerative diseases, including AD." (PMID 39385222, 2024). "Mutations resulting in the loss of p62/SQSTM1 function and impaired mitophagy lead to neurodegenerative diseases." (PMID 37507908, 2023). "The SQSTM1 gene encodes p62, a prototype autophagy receptor, which is commonly found in protein aggregates associated with major neurodegenerative diseases." (PMID 37304079, 2023). "P62 (SQSTM1) had been demonstrated that it was associated with neurodegenerative disease by inducing autophagy and mitophagy dysfunction." (PMID 37946715, 2023). "Magi2, Kif5b, Sqstm1 and Rap1a are associated neuronal development and neurite outgrowth, and some have previously been implicated in the pathogenesis of neurodegenerative diseases." (PMID 36089582, 2022). "SQSTM1, also known as p62, is a ubiquitin binding protein that is present in a variety of ubiquitinated inclusions associated neurodegenerative diseases including ALS and FTD." (PMID 32733193, 2020). "The p62, also called sequestosome 1 (SQSTM1), plays crucial roles in the autophagy machinery, and its accumulation has been linked to neurodegenerative disease." (PMID 25863674, 2015). "A particularly vulnerable gene in this regard is SQSTM1 encoding the autophagy receptor p62 and whose pathogenic variants are associated with the onset of various metabolic, myopathic and skeletal disorders as well as neurodegenerative disease including ALS." (PMID 35563729, 2022). "SQSTM1 has also been linked to other neurodegenerative diseases including AD, PD, and HD." (PMID 36421678, 2022). "This neurodegenerative disease, caused by biallelic SQSTM1 mutations, is panethnic." (PMID 33135846, 2020). "As previously reported, loss of p62/SQSTM1 leads to increased oxidative stress, possibly eliciting a stress-induced senescence response in astrocytes, which can also contribute to the progression of AD and other neurodegenerative diseases." (PMID 32727065, 2020). "Therefore, mutations of SQSTM1 are closely linked to neurodegenerative diseases through the autophagy failure." (PMID 33135846, 2020). "This progressive childhood neurodegenerative disease caused by SQSTM1 mutations is rare." (PMID 33135846, 2020). "P62, also called sequestosome 1, is a ubiquitin-binding scaffold protein that colocalizes with ubiquitinated protein aggregates in many neurodegenerative diseases and proteinopathies of the liver." (PMID 39615682, 2024). "Consistently, gene mutations of autophagic receptors (e.g., SQSTM1 (sequestosome 1), OPTN (optineurin), NBR1 (neighbor of BRCA1 gene 1)) are closely associated with neurodegenerative diseases." (PMID 35845350, 2022). "Among these, ATGs (Autophagy-Related proteins), MAP1-LC3s (Microtubule-Associated Protein 1 Light Chain 3 proteins, hereafter referred to as LC3) and p62/SQSTM1 (sequestosome 1) have been previously analysed in detail in different neurodegenerative diseases." (PMID 30760781, 2019). "With respect to the relationship between SQSTM1 and neurodegenerative diseases, it has been demonstrated that SQSTM1-positive aggregates are accumulated in the spinal cord and brain of ALS and ALS/FTD patients." (PMID 29843805, 2018). "There is intriguing evidence suggesting that protein SQSTM1/p62, together with autophagy, has a role in the pathology of different degenerative diseases." (PMID 23922739, 2013). "By this weight of evidence, the CAAA variant needs to be further examined as a contributor to ALS disease mechanisms, particularly since SQSTM1 plays a critical role in autophagy, and mutations in this gene can be a direct cause of ALS and other neurodegenerative diseases." (PMID 35034660, 2022).
neurodegenerative disease (continued). "Furthermore, the expression levels of p62/SQSTM1 are known to be decreased in several neurodegenerative diseases owing to age-related oxidative damage to DNA." (PMID 34377675, 2021). "Similarly, by analysing candidate genes involved in neurodegenerative diseases including those encoding proteins overrepresented in rimmed vacuoles, rare missense variants in the VCP and sequestosome 1 (SQSTM1) could be confirmed using whole-exome sequencing (WES) data of IBM patients." (PMID 36399165, 2023). "By regulating SQSTM1 and HSPA5 ubiquitination and regulating SQSTM1 activity, UBE2D3 could potentially contribute to clearance of aggregates and thereby help in reducing the chance of development of neurodegenerative diseases." (PMID 37059365, 2023). "SQSTM1 showed a behavior similar to that of RE C9orf72, sharing with the major ALS genes a young AAO of the affected patients, but with a rare family history for other neurodegenerative diseases." (PMID 33770234, 2021). "Future analyses of the interactomes of wild-type and mutant SQSTM1, TBK1 and VCP are needed to pinpoint how these proteins cooperate in a common complex with OPTN and UBQLN2 and how alterations in this complex may lead to ALS or other neurodegenerative diseases." (PMID 27164932, 2016).
myopathy (12 papers, 2017 to 2025). A disease of the muscle in which the muscle fibers do not function properly. "Only two previous studies illustrated myopathies associated with SQSTM1 variants (c.1165+1 G>A, c.1175C>T)." (PMID 36998782, 2023). "As previously reported, myopathy-related SQSTM1 variants have the following pathological features: myofiber size variations, partially decreased NADH enzyme reactivity, and the presence of rimmed vacuoles, suggesting compensatory autophagic reactivity." (PMID 36998782, 2023). "MATR3 mutation-associated myopathy was associated with the same distal limb weakness as previous SQSTM1-related cases, while the present case revealed proximal myopathy." (PMID 36998782, 2023). "Herein, we describe a patient with proximal myofibrillar myopathy caused by a novel, heterozygous frameshift mutation in SQSTM1, expanding the clinical, pathological, and mutational spectrum of associated disorders." (PMID 36998782, 2023). "The findings indicate that all the affected individuals have a myopathy associated with both variants in SQSTM1 and TIA1, respectively, suggesting that the two variants determine the phenotype and likely functionally interact." (PMID 29599744, 2018). "The lack of functional studies is certainly a limiting feature of the study, and further investigations will be needed to prove the digenic nature of the myopathy and the deleterious effects of the combined SQSTM1 and TIA1 variants in myopathy." (PMID 29599744, 2018). "The combination of TIA1 and SQSTM1 variants tend to result in myofibrillar myopathy." (PMID 36998782, 2023). "Such difference, however, could be due to the fact that 5 of the 6 patients in the non‐VCP MSP group had the SQSTM1+TIA1 mutations associated with late‐onset myopathy and therefore skewing the results." (PMID 36861178, 2023). "Compared with VCP myopathy, also known as inclusion body myopathy (IBM), the most common myopathy of MSP with symmetric muscle involvement, the proband's myopathy was asymmetric and had p62/SQSTM1 inclusions in the myofibers." (PMID 36998782, 2023). "Mutations in SQSTM1/p62, ubiquilin-2 and VCP are all associated with familial forms of ALS, FTD or myopathy." (PMID 28420962, 2017). "Interestingly, miR-16 is also connected to SQSTM1, of which the encoded protein is aggregated in IBM and other myopathies." (PMID 39815348, 2025). "These three genes have not been associated with PDB; isolated TIA1 mutations (without co‐existing pathogenic SQSTM1 variant) have not been reported as causative of both myopathy and ALS/FTD within the same pedigree." (PMID 36861178, 2023). "However, in light of our observation, we suggest that SQSTM1/TIA analysis is included in the molecular investigations of myofibrillar myopathies." (PMID 29599744, 2018). "Herein, we describe the clinical and pathological phenotype of three unrelated probands harboring the combined heterozygous TIA1 and SQSTM1 variants in the setting of MRV or myofibrillar pathology, providing evidence that co-occurrence of these variants are associated with late-onset myopathy." (PMID 29599744, 2018). "However, molecular and functional studies to dissect the likely interaction between TIA1 and SQSTM1 would shed light on the pathomechanism of the myopathy." (PMID 29599744, 2018). "Distal myopathy occurred in 10 patients (5 TIA1, 2 SQSTM1 + TIA1, 1 MATR3, 1 HNRNPA1, 1VCP)." (PMID 36861178, 2023). "Although the causality of the coexisting SQSTM1 and TIA1 variants in myopathy has not been proven, our affected individuals from three unrelated family provide further support to the digenic nature of this myopathy." (PMID 29599744, 2018). "One patient carried SQSTM1 c.1160C > T, p.Pro387Leu (Family 16/ patient 19), which was previously observed in individuals with PDB and FTD but not previously reported in the setting of myopathy." (PMID 36861178, 2023).
neurological disorders (6 papers, 2020 to 2025). "Many genes play an important role, with TARDBP, SQSTM1, VCP, FUS, TBK1, CHCHD10, and most importantly, C9orf72 being critical genetic players in these neurological disorders." (PMID 33805659, 2021). "TARDBP, SQSTM1, VCP, FUS, TBK1, CHCHD10, and most importantly C9orf72, are the critical genetic players in these neurological disorders." (PMID 32116499, 2020). "It is assumed that the development of these neurological diseases is due to impaired fusion of autophagosomes with lysosomes (inhibition of the NF-kB signaling pathway is enhanced), but the mutant TBK1, OPTN, and SQSTM1 genes also contribute to the pathogenesis." (PMID 39403278, 2024).
bacterial infections (2 papers, 2021 to 2025). "Regardless of the response pattern, the combination of the responses of SQSTM1, RNASE2, and GATA1 to BYBG supplementation may improve the innate immune capacity to respond to future bacterial infections, which is a hallmark of innate immune training." (PMID 39846553, 2025). "In addition, extracellular SQSTM1 is an inflammatory mediator in mice with bacterial infections, and the lysosome-dependent release of SQSTM1 induced by LPS in macrophages is initiated by STING1-TBK1–mediated phosphorylation of SQSTM1 on Ser 40331." (PMID 34078874, 2021).
cardiac diseases (2 papers, 2023 to 2025). "SQSTM1/p62 primarily plays a role in heart diseases through autophagy, and currently, there is insufficient evidence to support the role of SQSTM1/p62 in congenital heart diseases through ferroptosis." (PMID 37920788, 2023).
bone disorder (1 paper, 2021). "Mutations in the gene coding for SQSTM1/p62 have been found in approximately 10% of PDB patients, and a mouse model carrying the P394L mutation exhibits a PDB‐like bone disorder with focal bone lesions, linked to enhanced autophagy activation in osteoclasts and detrimental bone remodeling." (PMID 34459017, 2021).
gastrointestinal tumors (1 paper, 2021). "Expression of the 4 autophagy-related genes (SQSTM1, BIRC5, NRG3, and CXCR4) can accurately predict the prognosis of gastrointestinal tumors in Asian patients." (PMID 34484469, 2021).
neuromuscular disease (1 paper, 2025). "There is growing recognition that autophagy-related genes, including SQSTM1, may act as modifiers of neuromuscular disease or contribute to atypical clinical phenotypes, particularly in patients who lack common autoantibodies or clear structural abnormalities." (PMID 40772172, 2025).
retinopathy (1 paper, 2019). "The administration of a p62/SQSTM1-encoding plasmid in OXYS mice decreased the incidence and severity of retinopathy and downregulated proinflammatory cytokines." (PMID 31249643, 2019).